ATOX1 (antioxidant 1 copper chaperone)
Diseases named in the same sentence as ATOX1 in open-access papers (continued):
Sharing a sentence is not in itself a finding about the gene and the disease.
tumor (continued). "Among these, ATOX1 is most outstanding since its expression was higher in tumor compared to normal tissues in 53% (out of 19 cases) of matched clinical samples analyzed." (PMID 20543960, 2010). "Although the therapeutic strategies directly targeting ATOX1 are still immature, given the key position of copper metabolism in tumours, regulating ATOX1 is undoubtedly one of the feasible strategies to indirectly influence tumour progression." (PMID 40940984, 2025). "Furthermore, GEPIA database analysis revealed that the ATOX1 gene was substantially expressed in DLBCL tumor tissues." (PMID 39036924, 2024). "GEPIA database showed that ATOX1 gene was highly expressed in the tumor tissues of DLBCL." (PMID 39036924, 2024). "In addition, the copper-dependent transcription factor ATOX1 can be involved in tumor angiogenesis and vascular remodeling by regulating the platelet-derived growth factor (PDGF) signaling pathway." (PMID 37427098, 2023). "Considering copper involvement in the functioning of the LOX protein which is responsible for cell migration, ATOX1 may facilitate the function of LOX enhancing tumor ability for metastasis." (PMID 36296659, 2022). "ATOX1 expression was found and evaluated for both nucleus and cytoplasm of the tumor cells." (PMID 34944703, 2021). "We performed a semi-quantitative evaluation of ATOX1 staining intensities in the tumor cells only, considering both nucleus and cytoplasm, using intensity scores ranging from 0 to 3 representing negative, weak, intermediate and high staining intensities, respectively." (PMID 34944703, 2021). "Moreover, an increase in SOD1 and ATOX1 expression has been suggested to confer cisplatin resistance to tumor cells." (PMID 32155756, 2020). "The mechanisms by which the drug hits inhibit ATP7B trafficking remain unclear except for Tranilast, which reduces ATOX1 expression in resistant tumor cells." (PMID 32155756, 2020). "In addition, we scored the percentage of tumor cells with the strongest ATOX1 staining intensity as a measure for tumor heterogeneity and found a high level of tumor homogeneity, with an average of 79% and 82% considering nuclear and cytoplasmatic ATOX1 levels, respectively." (PMID 34944703, 2021). "Visual inspection of the stained tumor sections indicated ATOX1 expression to vary between different tissue sections from negative to strong staining intensities and to be homogeneous within each tissue section, with comparable ATOX1 staining intensity in inner tumor and tumor border." (PMID 34944703, 2021). "Suppression of ATOX1 might also help to combat tumor growth through additional mechanisms." (PMID 32155756, 2020). "Silencing ATOX1 inhibits stimulation of migration in smooth muscle cells of blood vessels through the action of PDGF, suggesting its crucial role in tumor angiogenesis." (PMID 40370501, 2025). "Research shows that the regulation of Cu chaperones ATOX1 and CCS is elevated in CRC, uterine cancer, and liver cancer, leading to increased activity of Cu-dependent enzymes and promoting tumor cell proliferation and metastasis." (PMID 40370501, 2025). "In xenograft models, tumor size was markedly smaller in the DCAC50-treated group compared to the control group, confirming the role of ATOX1 in promoting tumor growth in vivo." (PMID 40002764, 2025). "Conversely, silencing ATOX1 or inhibiting ATP7A activity can reduce LOX function and inhibit tumor cell proliferation and migration." (PMID 39691393, 2024).
tumor (continued). "Bioinformatics and in vitro experiments confirmed elevated expression of ATOX1 in DLBCL cells and tumor samples." (PMID 39036924, 2024). "In a further way, copper can also promote the synthesis of FGF-1 through ATOX1 and superoxide dismutase 1 (SOD1) to affect vascular endothelial function, while increasing the invasive and metastatic capacity of tumor cells by activating lysyl oxidase (LOX)." (PMID 37476384, 2023). "Out of the identified regulators, six genes (SLC6A3, MITD1, CCS, LIPT2, ATOX1, and GLS) showed increased expression in tumor tissues, while PDHB had higher expression in normal tissues." (PMID 38159255, 2023). "The results show a significant increase in the expression of SLC3A3, MITD1, LIPT2, ATOX1, PDHB, and GLS in tumor tissues compared to normal esophageal tissues." (PMID 38159255, 2023). "Providing that Atox1 and CCS copper chaperones are essentially engaged in trafficking of cisplatin and in its targeting to specific molecules, their cognate gene mutations, deletions or downregulations may render tumor cells refractory to cisplatin-based therapy." (PMID 31575544, 2019). "Moreover, ATOX1/ROCK1-targeted drugs’ therapeutic effects were further investigated in the LLC allogeneic transplantation model and MNU-induced tumour model." (PMID 40940984, 2025). "Co-inhibition of ATOX1 and ROCK1 either by siRNA transfection or inhibitory drugs could lead to a significant decrease in tumour proliferation." (PMID 40940984, 2025). "Some proteins from this list have also been identified in tumor studies as clinical outcome predictors (NOV, CLU TNC, POSTN, IGFBP2, LCN2) or mediators of resistance to chemotherapy (CLU, FBLN1, THBS, STIP1, PTGES3, IGFBP4, ATOX1)." (PMID 19936259, 2009). "In this respect, ATOX1 plays an important role in vascular remodeling by promoting copper- and RAS-related C3 botulinum toxin substrate 1 (RAC1)-dependent migration of vascular smooth muscle cells, macrophage infiltration and LOX activation, thereby contributing to tumor angiogenesis." (PMID 40721800, 2025). "Depending on tissue settings and genetic contents, Atox1 and CCS chaperones can control cisplatin trafficking routes and targeting efficiencies, thus indicating their essential contribution to acquired resistance of tumor cells to cisplatin-containing therapeutic regimens." (PMID 31575544, 2019).
genetic disorders (1 paper, 2023). "This enables zinc to bind excess copper, which avoids genetic disorders and releases oncogenic enzymes, such as ATP7A, ATP7B, CTR1, and ATOX1, to regulate homeostasis." (PMID 37049685, 2023).
infection (1 paper, 2016). The state of being infected such as from the introduction of a foreign agent such as serum, vaccine, antigenic substance or organism. "Interestingly, our RT-qPCR data reveals that the meta-genes ATOX1, OAS2 and USP18 were consistently up-regulated with a distinct pattern with infection time-course in THP-1 cells infected with DENV-1 or DENV-2." (PMID 27651116, 2016).
neurodegenerative disease (1 paper, 2015). A disorder of the central nervous system characterized by gradual and progressive loss of neural tissue and neurologic function. "Therefore, we propose the potential efficacy of Tat-Atox1 protein as a therapeutic agent for the treatment of a variety of neurodegenerative diseases." (PMID 25781353, 2015).
ATOX1 also shares sentences with these, for which no sentence is quoted: adenocarcinoma (1 paper); African trypanosomiasis (1); Alzheimer disease (1); hepatocellular carcinoma (1); inflammatory bowel disease (1); invasive breast carcinoma (1); leukemia (1); multiple sclerosis (1); myeloid leukemia (1); neuroblastoma (1); neurological disorders (1); pulmonary hypertension (1); trisomy 21 (1).